ATF6 (activating transcription factor 6)
Diseases named in the same sentence as ATF6 in open-access papers (continued):
Sharing a sentence is not in itself a finding about the gene and the disease.
breast cancer (continued). "However, the importance of ATF6 in breast cancer requires further study, because to date, there has been no study reporting the role of ATF6 in breast cancer." (PMID 32376943, 2020). "Thus, we evaluated the intracellular signaling pathways involved in UPR (e.g., Inositol Requiring 1 (IRE1), PKR-like ER Kinase (PERK), and Activating Transcription Factor 6 (ATF6)) after leptin treatment in breast cancer cells without find any activation." (PMID 31336913, 2019). "Inhibition of p38 blocked the carnosol-induced activation of IRE-1α and ATF6 sensors without affecting the CHOP activation, decreased UPS activity and blocked autophagy, as well as attenuated cell death in breast cancer cells." (PMID 35712465, 2022). "There is no direct evidence that ATF6 plays a role in drug-resistance, although one study found ATF6 to be an independent predictor of increased relapse and shorter survival in primary ESR1+ breast cancers treated with tamoxifen." (PMID 30248920, 2018).
melanoma (31 papers, 2009 to 2025). A malignant, usually aggressive tumor composed of atypical, neoplastic melanocytes. "Sustained induction of IRE1 and ATF6 is linked to increased MEK/ERK activation that protects melanoma from UPR-induced apoptosis, while inhibition of MEK/ERK partially blocks IRE1 and ATF6." (PMID 26927180, 2016). "Other studies have demonstrated a vital protective role through targeted downregulation of ATF6, which results in increased melanoma cellular sensitivity to the ER stress inducers: thapsigargin and tunicamycin." (PMID 39530163, 2025). "It has been also demonstrated that sustained activity of IRE1α (inositol-requiring enzyme 1 alpha) and ATF6 (activating transcription factor 6) promotes adaptation of melanoma cells to proteotoxic stress, which supports cancer progression." (PMID 31659567, 2020). "ATF6−/− and IRE1α−/− melanoma cells showed increased sensitivity to ER stress in the presence of adequate PERK signaling." (PMID 31227689, 2019). "ATF6 are reported to contribute to enhanced viability in glioblastoma, and important for survival of melanoma cells undergoing ER stress." (PMID 28629319, 2017). "Kaplan-Meier analyses show decreased survival of melanoma patients with high mRNA levels of ATF6 and its down-stream target GRP78." (PMID 29235576, 2017). "It has recently been reported that MEK/ERK signaling plays a role on ATF6 activity in human melanoma cells." (PMID 26105053, 2015). "Instead, the ATF6/IRE1α/XBP-1 axis of the UPR appears to play an important role in up-regulation of TRAIL-R2 induced by 2-DG in melanoma cells." (PMID 20003459, 2009). "As with TM and TG, 2-DG-induced up-regulation of TRAIL-R2 in melanoma cells was partially inhibited by siRNA knockdown of IRE1α or ATF6, indicating that these pathways of the UPR are involved in up-regulation of TRAIL-R2 by 2-DG." (PMID 20003459, 2009). "Further investigating the apoptotic phenotype after the loss of PHF5A in melanoma cells, our study revealed that the knockdown of PHF5A leads to an activation of the unfolded protein response (UPR) via PERK and ATF6‐signalling pathways with an increased expression of C/EBP Homologous Protein (CHOP)." (PMID 39212334, 2025). "We could show an increased amount of cleaved ATF6 (ATF6‐N) as well as a reduction of full‐length ATF6 on protein level after knockdown of PHF5A, indicating that a loss of PHF5A in melanoma cells activates also this second UPR pathway." (PMID 39212334, 2025). "Moreover, previous studies have suggested that sustained activation of ATF6 is a prosurvival mechanism in various cancer types such as melanoma, glioblastoma, and hepatocellular carcinoma." (PMID 37704840, 2023). "To further understand the biological connection between PTEN and Entpd5/IGF1R pathway, we first assessed the expression levels of ATF6 in melanoma cells carrying the various PTEN mutants by western blot; ATF6 expression was reduced in PTEN WT cells, but enhanced in PTEN ΔLP cells." (PMID 36824269, 2023). "However, a pro-survival role for ATF6 has been observed in response to chronic, mild ER stress, and knockdown of ATF6 was reported to sensitize melanoma cells to apoptosis induction by Tm or Tg." (PMID 31987044, 2020). "In addition, it has been demonstrated that oncogenic MAPK signaling increases intracellular protein load and maintains cytoprotective autophagy at elevated level, and sustains IRE1α and ATF6 at activated states to adapt melanoma cells to a chronic ER stress." (PMID 30989459, 2019). "Additionally, increased and sustained activation of other UPR mediators, IRE1 and ATF6 are critical for melanoma survival." (PMID 26927180, 2016). "Combined with the up regulation of signaling IRE1 and ATF6, it can be speculated that MEL-A-induced B16 melanoma cell apoptosis was associated with the endoplasmic reticulum stress (ERS)." (PMID 26828792, 2016). "In addition, persistent activation of ATF6 and reduced apoptosis were revealed in tunicamycin or thapsigargin-treated melanoma." (PMID 26622781, 2015).
melanoma (continued). "In addition, oncogenic activation of MEK/ERK signaling contributes to sustain the activation of IRE1α and ATF6, which is important for melanoma cell survival and promotes the pathogenesis of melanoma." (PMID 26105053, 2015). "Moreover in melanoma cell lines, the activation of ATF6 is also modulated by MEK/ERK signaling and thus conditioned by BRAF mutation status." (PMID 25437182, 2014). "In parallel, the overexpression of SIRT7 in WM35 melanoma cell line resulted in up-regulation of IRE1α expression, IRE1α phosphorylation, spliced XBP1 expression, and HSPA5 expression caused by TM treatment, but marginal influence on ATF6 and phosphorylated-PERK." (PMID 36918544, 2023). "Altogether, our data indicate that PTEN phosphatase activity inhibits metastasis by negatively regulating the Entpd5/IGF1R pathway through ATF6, thereby identifying novel candidate therapeutic targets for the treatment of PTEN mutant melanoma." (PMID 36824269, 2023). "We found that ER proteins IRE1α, Atf6, Calnexin, and CHOP are all equally expressed in resistant melanoma cells." (PMID 34282258, 2021). "As both IRE1α and ATF6 can upregulate expression of GRP78 in melanoma, the contribution of IRE1α to the increase in GRP78 mRNA level is more likely because ATF6 activity remained unaltered following 17-aminogeldanamycin treatment." (PMID 30989459, 2019). "In primary tumours of human melanoma patients, the expression of both FGF1 and FGF2 mRNA displayed a significant positive correlation with the expression of down-stream targets of the ATF6 and PERK branches of the UPR." (PMID 29235576, 2017). "Consistently, FGF expression positively correlated with the activity of ATF6 and PERK in human melanomas." (PMID 29235576, 2017). "Another potential candidate marker is ATF6 which acts as sensor of the Endoplasmic Reticulum (ER)-induced Unfolded Protein Response (UPR) whose role in the different phases of tumor and melanoma growth is well known." (PMID 25437182, 2014). "Consistent with our in vitro findings, genes associated with the ATF4 (e.g., ATF4, DDIT3, PPP1R15A and CHAC1), ATF6 (e.g., ATF6B, CALR, SEL1L, and EDEM1) and XBP1 (e.g., SSR3 and DELR1) pathways were significantly enriched in melanoma TILs compared with healthy blood T cells." (PMID 40335738, 2025). "First, we assessed the consequences of CAP on the unfolded protein response (UPR) by analyzing its three main signaling pathways PERK (PKR-like endoplasmic reticulum kinase), ATF6 (Activating transcription factor 6), and IRE1 (Inositol-requiring enzyme 1) in the melanoma cell line Mel Juso." (PMID 36831408, 2023). "We also examined the ATF6 expression in human melanoma by immunohistochemistry using serial tissue microarray sections compared with PTEN, Entpd5 and IGF1R, and found that the ATF6 expression negatively correlated with PTEN expression, while positively with Entpd5 and IGF1R." (PMID 36824269, 2023). "Knowledge of the status of the PTEN/ATF6/Entpd5/IGF1R axis may prove to be valuable in the design of novel preventive and interventive therapeutic strategies in melanoma." (PMID 36824269, 2023). "Moreover, XBP-1, which is known to be transcriptionally regulated by ATF6 and functionally activated by IRE1α, was found to play an important role in 2-DG-mediated transcriptional up-regulation of TRAIL-R2 in melanoma cells." (PMID 20003459, 2009). "We here show that ATF6 could directly bind to the Entpd5 gene promoter and regulate its expression, linking the UPR signaling-folding protein promoter Entpd5 to cell survival and metastasis of melanoma cells." (PMID 36824269, 2023). "Notably, we demonstrate that PTEN phosphatase negatively regulates the protein N-glycosylation and folding promoter Entpd5 and the Entpd5/IGF1R pathway through Atf6 transcriptional regulation, identifying an important new mechanism by which PTEN inhibits melanoma metastasis." (PMID 36824269, 2023).
melanoma (continued). "In addition, HA15, a small molecule that activates ER stress by inhibiting the interaction between BIP and ER stress sensors (PERK, IRE1, and ATF6), was lethal to melanoma but not non-tumorigenic melanocytes." (PMID 32626657, 2020). "This might also explain our observed activation of all three UPR branches in metastatic compared to non-metastatic cells, while only the induction of the ATF6- and PERK-, but not the IRE1-pathway, is associated with poor survival in melanoma patients." (PMID 29235576, 2017). "The activity of the ATF6- and the PERK-, but not the IRE-pathway, correlated with poor survival in melanoma patients." (PMID 29235576, 2017).
Insulin resistance (29 papers, 2012 to 2026). Increased resistance towards insulin, that is, diminished effectiveness of insulin in reducing blood glucose levels. "Insulin resistance in podocytes specifically promotes activating transcription factor 6 (ATF6) dependent pathogenic UPR." (PMID 35455399, 2022). "ATF6 is associated with an adaptive response to endoplasmic reticulum (ER) stress and is concomitant with the induction of insulin resistance in skeletal muscle." (PMID 33153045, 2020). "Interestingly, ATF6 deficiency alters the expression of ER chaperones and exacerbates liver injury, necroptosis, impaired fatty acid oxidation, steatosis and insulin resistance arising from acute stress." (PMID 37020593, 2023). "Insulin resistance caused by the saturated fatty acid palmitic acid also caused ER stress as indicated by an increased mRNA and protein expression of the ER stress-markers ATF6, ATF3, GRP78, CHOP, and Tribbles 3 (TRIB3) in C2C12 myotubes." (PMID 35615361, 2022). "Therefore, we suspect that CACE can suppress the activation of PERK- and ATF6-associated ER stress pathways, leading to protect cells against ER stress-induced cell apoptosis and improve cells to recover insulin resistance." (PMID 33688365, 2021). "In addition, ATF6α deficiency can improve insulin sensitivity and restrain the development of insulin resistance." (PMID 33688365, 2021). "Furthermore, when fed with a high fat diet, ATF6α null mice developed insulin resistance associated with impaired insulin secretion and lower insulin content, reinforcing the idea of a key role of ATF6α in β cells adaptation and insulin resistance." (PMID 24812634, 2014). "ER stress response through ATF6 has been shown to play an important role in insulin resistance and pancreatic β-cell function." (PMID 25302688, 2014). "Glucosamine-induced ER stress causes insulin resistance in both human and rat skeletal muscle and impairs GLUT4 production and insulin-induced glucose uptake via an ATF6α-dependent decrease of the GLUT4 regulators MEF2A and PGC1α." (PMID 23716639, 2013). "Even though insulin resistance precedes muscle wasting, it remains enigmatic whether ATF6-mediated insulin resistance fosters cachectic phenotype." (PMID 31817027, 2019). "In addition, physiological conditions like exercise induce GDF-15 could have a protective role against obesity and insulin resistance and also eliminate its reinforced stress markers like Atf3, Atf6, and Xbp1s in skeletal muscle after exercise." (PMID 38409184, 2024). "However, ATF6 protection against insulin resistance was not directly linked with its function in ERet stress." (PMID 36359245, 2022). "Thus, whether ATF6 mediated insulin resistance promotes cachectic conditions during cancer remains to be investigated, although ATF6 levels have been found to remain elevated in mice bearing LLC tumor as well as in APCMin/+ cancer models of cachexia." (PMID 31817027, 2019). "Hyperglycemia leads to elevated glucosamine levels that are also able to induce insulin resistance and ER stress as indicated by an increased expression of the ER stress markers GRP78/BiP, XBP1 and ATF6 in both human and L6 myotubes." (PMID 35615361, 2022). "Such interactions include ATF6α-mediated upregulation of mTORC1 and UPR activation contributing to insulin resistance." (PMID 30606258, 2019). "An impaired insulin signaling secondary to insulin resistance promotes a maladaptive UPR with an impaired spliced XBP1 nuclear translocation and is characterized by ATF6 and CHOP signaling in diabetic nephropathy." (PMID 26545114, 2015). "ER stress and unfolded protein response play significant roles in insulin resistance aggravation through the activation of apoptosis, inflammatory response, and insulin signaling impairment mediated via IRE1/PERK/ATF6 signaling pathways and the upregulation of SREBP 1c." (PMID 37998747, 2023).
Insulin resistance (continued). "Further study showed that the decreased concentration of serum ceramide could regulate the hepatic endoplasmic reticulum stress- (ERS-) related proteins, including PERK, ATF6α, CHOP, and GRP78 BIP, and then reduce ER stress induced by high-fat diet and insulin resistance." (PMID 34422083, 2021).
achromatopsia (26 papers, 2017 to 2025). Achromatopsia (ACHM) is a rare autosomal recessive retinal disorder characterized by color blindness, nystagmus, photophobia, and severely reduced visual acuity due to the absence or impairment of cone function. "Hearing loss was reported by 3 achromatopsia siblings homozygous for a c.970C>T ATF6 variant that introduced an arginine-to-cysteine conversion at position 324 (II:1, II:2, and II:3)." (PMID 39570676, 2025). "Hearing loss was a prominent complaint in multiple patients with achromatopsia carrying ATF6 disease variants." (PMID 39570676, 2025). "In people, cone photoreceptors require ATF6 for development and function, and loss of ATF6 leads to congenital vision loss diseases like achromatopsia." (PMID 39570676, 2025). "ATF6 inactivating patient mutations cause a blindness-deafness genetic syndrome characterized by cone photoreceptor dysfunction achromatopsia and sensorineural hearing loss." (PMID 39570676, 2025). "Previous evidence shows that people carrying loss-of-function ATF6 disease alleles have congenital vision loss, achromatopsia, and cone-rod dystrophy." (PMID 39895634, 2025). "Recent studies have shown that ATF6, which is a major transcriptional regulator of p58IPK, is required for cone development and function and mutations of ATF6 cause achromatopsia, an autosomal recessive cone dysfunction disease." (PMID 37371028, 2023). "Atypical foveal hypoplasia has been described in achromatopsia and cone-rod dystrophy, particularly in patients with a mutation of the encoding activating transcription factor 6A (ATF6) gene." (PMID 36836571, 2023). "A phenotypic correlation is seen in patients with ATF6 mutation-induced achromatopsia who present foveal hypoplasia, supporting a role of ATF6 in cone development." (PMID 35346303, 2022). "Six genes have been identified in close association with achromatopsia, including the gene encoding ATF6." (PMID 35346303, 2022). "Recent investigations into the associations between ATF6, photoreceptor integrity, and achromatopsia reveal the diversity among the roles and potential mutations of ATF6." (PMID 35346303, 2022). "Concerning the ATF6 sensor, an ATF6-mediated stress response has been shown to be essential for color vision in humans since mutation in this genes results in achromatopsia." (PMID 34439418, 2021). "Variants in the human ATF6 gene cause achromatopsia and cone-rod dystrophy carrying bi-allelic disease alleles." (PMID 34381136, 2021). "Perhaps most significantly, mutations to ATF6 cause achromatopsia and result in loss of cone photoreceptor cells." (PMID 31852729, 2020). "Patients carrying a [D564G] mutation within the ATF6α lumenal domain suffer from a heritable blinding disease called achromatopsia." (PMID 31368601, 2019). "The critical importance of ATF6-regulated processes to human health is exemplified by the occurrence of achromatopsia in individuals harbouring ATF6 mutations." (PMID 29801500, 2018). "Although ATF6 is essential for regulating ER stress in retinal photoreceptors, the mechanisms behind ATF6-associated achromatopsia and its preference for central cone photoreceptor degeneration remains unclear." (PMID 35346303, 2022). "In addition, ATF6, a recessive achromatopsia-associated gene, was selectively expressed in human GCs located in the periphery, but showed no obvious expression in macaques." (PMID 34691611, 2021). "This is in part supported by several recent reports identifying mutations of human ATF6 that interrupt the proper activation of this UPR molecule during ER stress contributing to the development of achromatopsia, an autosomal recessive retinal disease characterized by cone dysfunction." (PMID 29615095, 2018).